ALB (albumin)
Diseases named in the same sentence as ALB in open-access papers (continued):
Sharing a sentence is not in itself a finding about the gene and the disease.
anemia (continued). "Among the clinical parameters, the presence of low albumin was selected as an indicator of nutritional status, and hemoglobin level, which was clinically easy to interpret, was selected as an indicator of anemia." (PMID 38982532, 2024). "Based on our center’s data, advanced pancreatic cancer patients undergoing two cycles of chemotherapy with albumin-bound paclitaxel and gemcitabine have a 69% incidence rate of anemia." (PMID 39075587, 2024). "Laboratory and imaging tests revealed a decreased incidence of anemia, decreased albumin levels, elevated globulin levels, elevated LDH levels, elevated CRP levels, increased polyclonal serum immunoglobulin levels, and advanced disease stage." (PMID 38601148, 2024). "Stratified analyses showed that the association between LDH and the risk of DKD in patients with T2D varied by age (‘<60’,’≥60’ years), sex (‘male,’ ‘female’), serum albumin (‘<35’,’≥35’ g/L), anemia (‘yes’." (PMID 38567310, 2024). "Patient-related risk factors included lower preoperative hemoglobin, American Society of Anesthesiologists (ASA) Physical Status > 2, anemia, lower preoperative fibrinogen, and lower preoperative albumin." (PMID 38840126, 2024). "Patients with SARC-F scores ≥ 4 and MISs ≥ 6 were older and had significantly lower albumin and prealbumin levels, as well as more severe anemia." (PMID 39337040, 2024). "We observed a reversed albumin/globulin ratio, hypocalcemia, and anemia of chronic disease accompanied by mild rouleaux formation." (PMID 39058808, 2024). "Blood biochemistry tests revealed anemia, renal dysfunction, increased inflammation, and a protein-albumin discrepancy." (PMID 38440032, 2024). "Lower hemoglobin and albumin would indicate a worse condition to face the infection, likewise a state of prolonged infection exacerbates catabolism that worsens the condition of anemia and chronic malnutrition." (PMID 38833431, 2024). "In univariate analysis, > 3 comorbidities, CRP ≥ 12 mg/L, anemia, low serum albumin, and stages III-IV-V vs. I-II of renal failure were significantly associated with ID." (PMID 38287253, 2024). "Laboratory findings indicated severe anemia, thrombocytopenia, conjugated hyperbilirubinemia, low protein and albumin levels, and elevated liver enzymes." (PMID 39618628, 2024). "LYM, PLT, ALB, Ca, CREA, D‐dimer, ESR, PCT, and CA‐153 emerged as independent risk factors associated with anemia development post‐chemotherapy in osteosarcoma patients." (PMID 39621534, 2024). "Despite these points, we observed several comorbidities among our HD population such as anemia, hyperphosphatemia, low ALB, and elevated PTH." (PMID 37363538, 2023). "As emphasized earlier, leukopenia, lymphopenia, neutropenia, thrombocytopenia, anemia (both female and male), decreased ferritin, total protein, albumin, vitamin D, vitamin B12 and folate levels were most common in patients with normal body weight." (PMID 37762958, 2023). "Referring to our case, the patient complained of weight loss and fecal vomiting, and his laboratory tests were consistent with severe anemia and decreased serum albumin levels." (PMID 36689053, 2023). "As can be expected in mice with significant tumor burdens, mice across treatment groups had decreased albumin levels and evidence of mild marrow hypoplasia resulting in mild anemia, and reduced white blood cell and platelet counts." (PMID 37446056, 2023). "In univariate analysis, ECOG performance status ≥2, age >70 years, anemia, albumin level <35 g/L, platelet count <100 × 109/L, elevated LDH, and elevated β2‐MG were adverse prognostic factors for OS." (PMID 36106610, 2023). "Anemia (p < 0.001) and emergency surgery (p < 0.001) were more frequent and albumin level (p < 0.001) was lower in the AKI group." (PMID 36615159, 2023). "Six independent parameters predicting prognosis were age, pack-years, N stage, lymph node ratio (LNR), anaemia and albumin." (PMID 37898687, 2023).
anemia (continued). "Initial laboratory results indicated anemia with leukocytosis, raised inflammatory markers, and low serum albumin." (PMID 38074029, 2023). "The HALP score combines hemoglobin, albumin, lymphocyte and platelet counts, reflecting the degree of anemia, nutritional status, immune status and coagulation function, which is a comprehensive score." (PMID 37746281, 2023). "Patients with higher inflammatory markers (according to CRP, NLR or their combination) had more anemia, more fever and number of infections and lower albumin as expected." (PMID 37016028, 2023). "TA-TMA was suspected because of anemia, thrombocytopenia, hypertension, gastrointestinal bleeding, decreased serum albumin, and raised lactate dehydrogenase." (PMID 36915123, 2023). "Inflammation reduces ALB synthesis, leading to a decrease in serum ALB concentration, and high production of cytokines limits iron uptake and inhibits erythrocyte maturation, which can further lead to anemia." (PMID 38028472, 2023). "The results of our study showed that the percentage of patients with BMI <18.5 increased (26.2% vs. 16.9%), the anemia rate increased (42.4% vs. 32.6%), and the rate of albumin reduction <35.0 g/L increased (33.7% vs. 26.7%)." (PMID 37577279, 2023). "Ferritin is a blood protein that contain iron leading to anaemia if low blood ferritin level and albumin is a protein made by liver used as storage reservoir of proteins and transporter of amino acids." (PMID 38014372, 2023). "Red blood cell count, hemoglobin, albumin, and calcium ion values were lower in patients with more severe disease, suggesting a tendency toward anemia and abnormal hepatic function." (PMID 36817453, 2023). "Albumin levels, fluid overload, anemia from a bleed, and low platelets due to a transplant were other factors reported by RDs across hospitals to be associated with false positives." (PMID 37440303, 2023). "Anemia, white blood cell (WBC) count, blood platelet (PLT) level, hemoglobin (Hb) count, D-dimer, FDP, neutrophil count, and albumin level were all found to be associated with TTS." (PMID 37840936, 2023). "While laboratory results’ first canonical coefficients revealed a phenotype related to high creatinine levels with low albumin levels and anemia, on the clinical side, the patient appeared to be elderly and multi-morbid with moderate to severe renal disease." (PMID 38045288, 2023). "The prevalence of laboratory tests were as follows: albumin <35 g/L (55.6%), erythrocyte sedimentation rate >20 mm/h (91.4%), anaemia (59.0%), predominantly mild, CD4+ T cell count ≤50 pieces/μL (70.3%), and CD4+ T cell count 51-200 pieces/μL (22.1%)." (PMID 37651639, 2023). "The increased levels of CRP, anemia, and reduced levels of albumin are also due to increased level of IL-6, which leads to myocardial infarction and an extra-articular manifestation of RA." (PMID 37113751, 2023). "Concurrent with parvoviremia, she developed a second episode of TA-TMA manifested by circulating schistocytes, anemia, thrombocytopenia, low albumin, and an increase in lactate dehydrogenase and creatinine." (PMID 36915123, 2023). "The CCD group presented higher numbers of anemia (22.34 vs. 7.06%, p = 0.002) and lower levels of preoperative albumin (3.47 vs. 3.73, p < 0.001)." (PMID 37048726, 2023). "Patients with anemia have low blood albumin, eGFR, serum 25-hydroxyvitamin D, and low energy and protein intake." (PMID 36797683, 2023). "Laboratory data showed that the patient had severe anemia (hemoglobin: 4.0 g/dl) and malnutrition (albumin: 2.7 g/dl)." (PMID 36689053, 2023). "Higher BMI was associated with lower Hb, HCT, albumin, and WBCs, whereas the decreased levels of hemoglobin and HCT point to anemia, known to be prevalent in HIV patients, and the reduction in CD4+ T cell count indicates immunosuppression in the patients." (PMID 37736888, 2023).
anemia (continued). "Although pre-albumin and transferrin have been found to be prognostic for mortality, their turnover rate, half-life, and potential interference by inflammation and anemia substantially limit their universal use." (PMID 36771356, 2023). "Other factors that can contribute to the development of PAH by increasing cardiac output are anemia and low albumin." (PMID 36471276, 2022). "This process involves abnormalities of the multi-organ functions and mediates systemic inflammation, resulting in anorexia (nutritional deprivation), reduced albumin synthesis, or cancer-related anemia." (PMID 35804906, 2022). "In the univariate analysis, a low PWR, abscess size, anemia, albumin, ALP and CRP levels, K. pneumoniae infection and unidentified infection were associated with prolonged hospitalization for more than 14 days." (PMID 36292245, 2022). "In this study, PNI was evidenced to be an independent protective factor for kidney disease progression to ESRD in individuals with biopsy-confirmed DN and T2DM, even after adjustment for serum albumin and anemia." (PMID 36079889, 2022). "The child also had anemia, hyponatremia, low albumin and high globulin, slightly raised liver enzymes and alkaline phosphatase probably because of the fractures." (PMID 36539748, 2022). "Albumin, weight changes and anemia are indicators of the nutritional status and potential tumor cachexia." (PMID 35331196, 2022). "Other factors, including age, HTN, DM, the location and size of abscess, anemia, levels of albumin, AST, ALT, PT-INR, Cr, and CRP and infections with K. pneumoniae, E. coli and other organisms were not correlated with the development of pleural effusion." (PMID 36292245, 2022). "In the univariate analysis, an older age, HTN, location of the abscess, anemia, albumin levels, AST levels, ALT levels, CRP levels, K. pneumoniae infection and unidentified infection were significant factors contributing to the development of low PWR levels." (PMID 36292245, 2022). "Other common observations includedhypoalbuminemia defined as serum albumin under 26 g/L (80%), maternal anemia definedas maternal haemoglobin at the time of presentation of below 110 g/L (70%)." (PMID 36262819, 2022). "In the multivariate analysis, old age, anemia, albumin and CRP levels and unidentified pathogens were significant factors for low PWR levels." (PMID 36292245, 2022). "Stage, serum albumin, ALI, anemia, and surgery were independent risk factors for cachexia in patients with lung cancer." (PMID 35898878, 2022). "None of the other studies discussed here included blood test results, such as anemia, low albumin or high lactate dehydrogenase." (PMID 36290842, 2022). "Anemia correction and nutritional status tend to be well preserved in this daily treatment schedule, as indicated by mean values of hemoglobin and serum albumin." (PMID 35456216, 2022). "In the univariate analysis, a low PWR, abscess size, anemia, albumin level, ALP level, E. coli infection and infection with an unidentified organism were associated with the development of pleural effusion." (PMID 36292245, 2022). "Blood tests revealed anemia at 6.5 g/dL Hb and reduced albumin levels at 3.0 g/dL, and endoscopic examination identified multiple large polyps in the stomach, especially in the lower body and antrum." (PMID 35928693, 2022). "When these factors were included in multivariate logistic regression analysis, anemia, disease stage, albumin, ALI, and surgery served as independent predictors for cancer cachexia in lung cancer patients." (PMID 35898878, 2022). "Laboratory findings showed anemia, an increased platelet count, a decreased albumin level (1.6 g/dL), and elevated erythrocyte sedimentation rate (100 mm/hr) and CRP level (8.34 mg/dL)." (PMID 35757758, 2022). "The clinical manifestations at onset that were more prevalent among patients with sarcopenia than without included digital ulcer, hand deformity, low BMI (< 18.5 kg/m2), high mRSS, low serum albumin, and anemia." (PMID 36307496, 2022).
anemia (continued). "Laboratory workup revealed anemia, hyponatremia, low albumin, raised globulin, increased alanine aminotransferase (ALT), aspartate aminotransferase (AST) and D-dimers (DD)." (PMID 36539748, 2022). "The abnormalities frequently detected at the initial visit included: increased white blood cell count (>20,000/μL) (n = 7, 50%), anemia (hematocrit value less than 35%) (n = 5, 35%), and low plasma albumin level (less than 2.0 g/dL) (n = 2, 16%)." (PMID 36288164, 2022). "Preoperative erythrocyte abnormalities, anemia, albumin decreased in 77 (47%), 66 (40%) and 60 (36%) patients, respectively." (PMID 35739171, 2022). "Parallel improvement in anemia, albumin, eosinophil count and fecal α1AT level (where measured) was observed in all children." (PMID 35174199, 2022). "CKD-ND-related fatigue has a complex multifactorial etiology, including low albumin levels, anemia, and restless legs syndrome." (PMID 35361150, 2022). "Specifically, elevated monoclonal IgG levels at 5,103 mg/dL, anemia (hemoglobin 10.9 g/dL), and hypercalcemia (10.5 mg/dL with albumin correction) were indicative of MM." (PMID 35757758, 2022). "Consistent findings in blood samples from all clinically affected and clinically normal horses included borderline anaemia, leucocytosis, thrombocytosis, lymphocytosis, hyperfibrinogenaemia, hyperglobulinaemia and a reverse albumin: globulin (A: G) ratio." (PMID 32920897, 2021). "In CD patients, age of diagnosis (15y–younger than 18y) was a predictor of moderate to severe anemia and albumin levels (<33 g/L) were protective against anemia." (PMID 33467587, 2021). "These dogs also had significantly decreased albumin concentrations, and more evident anemia, characterized by lower erythrocyte count, hemoglobulin levels, and hematocrit." (PMID 34827938, 2021). "As the results are shown in this studies, osteoarticular TB will lead to anemia, low albumin, and low BMI." (PMID 34129634, 2021). "The AD group had profound lymphopenia and anemia, higher serum levels of creatinine, bilirubin, and lactate, greater international normalized ratio value, and lower serum albumin levels." (PMID 33723292, 2021). "In particular, mean corpuscolar hemoglobin concentration, albumin, and total protein resulted decreased in unhealthy compared to healthy centenarians, probably due to anemia and organ disfunction more pronounced in unhealthy status." (PMID 34160893, 2021). "Notable findings include increased inflammatory markers level as well as anemia and low serum albumin level." (PMID 34645482, 2021). "Anaemia, low albumin, raised PSA, history of ischaemic heart disease and smoking were also strongly associated with all-cause mortality, as were peripheral vascular disease, chronic obstructive pulmonary disease and beta-blocker use." (PMID 33579772, 2021). "Hematologic changes can include increased gamma globulin levels and decreased albumin, anemia, and thrombocytopenia." (PMID 34827938, 2021). "This multivariate analysis allowed the independent prognostic value for OS to be retained only for albumin level, anemia, and age (p = 0.001, p = 0.05, and p = 0.05, respectively)." (PMID 34502204, 2021). "Reduced levels of serum albumin and hematocrit indicate protein-losing enteropathy and anemia, respectively." (PMID 33494263, 2021). "Futhermore, postoperative careful incision care and timely correction of anemia or low serum albumin are also important to prevent complications of SSI." (PMID 34243798, 2021). "Of the indeterminate results, 32 (82%) had an elevated CRP (>10); 38 (97%) had a low serum albumin (<35); anaemia was present in 26 patients (67%); and thrombocythemia was found in 27 (69%) patients." (PMID 33919426, 2021). "Conversely, prevalence of anaemia was significantly higher in those requiring intervention than in the self-healing group (p < 0.03), while haemoglobin, iron, ferritin, and albumin levels were lower (p < 0.001, p < 0.05, p < 0.02, p < 0.007, respectively)." (PMID 34682146, 2021).
anemia (continued). "Multivariate analysis revealed that anaemia, low albumin and elevated d-dimer were independent predictors of CVST." (PMID 34417546, 2021). "Serum albumin levels decreased with worsening anaemia state, while the mean phosphate level progressively increased with increasing severity of anaemia." (PMID 35283988, 2021). "Anemia, lower serum albumin and lower basal oxygen saturation at admission were factors associated with poor prognosis." (PMID 33307933, 2021). "Conversely, a raised ESR is related to multifactorial mechanisms, including increased levels of fibrinogen, alpha-1 and gamma-globulins, as well as reduced plasma albumin and anaemia." (PMID 33569633, 2021). "The most significant abnormalities are anemia, increased C-reactive protein, and low serum albumin levels." (PMID 33923423, 2021). "Similar results were found in proteinuria > 1 g/d (p < 0.001), albumin < 30 g/l (p < 0.001), anemia (p < 0.001), uric acid (p < 0.001), and TG (p < 0.001) subgroups." (PMID 34869465, 2021). "Both anemia and lower serum albumin level were also found in elderly coronary artery disease patients who had cardiac sudden death." (PMID 34606471, 2021). "Anaemia (adjusted HR per SD 0.72; 95% CI 0.59 to 0.88) and low albumin (adjusted HR per SD 0.81; 95% CI 0.67 to 0.97) were also associated with this outcome." (PMID 33579772, 2021). "It is generally believed that early graft nephrectomy after GL can reduce the impact of inflammatory status in these patients and improve responsivity to anemia treatment and albumin levels, all markers of mortality in dialysis patients." (PMID 33471845, 2021). "IL-6 induces hepcidin and causes secondary anemia, promoting CRP production and inhibiting albumin production." (PMID 34117557, 2021). "Age of diagnosis (15 < 18) and albumin levels (<33 g/L) were predictors of moderate and severe anemia at diagnosis, and only with the CD cohort." (PMID 33467587, 2021). "The initial model included elderly, history of AF, history of AV blocks, value of albumin, eGFR, anemia determined by WHO criteria, moderate or severe PH, diuretics users, STS score and AS detected by heart murmur as independent variables." (PMID 33606827, 2021). "A blood examination showed severe anemia (hemoglobin level: 5.5 g/dL) and an unfavorable nutritional status (total protein: 4.5 g/dL, albumin level: 2.5 g/dL, pre-albumin: 16.7 mg/dL)." (PMID 33409765, 2021). "Recent recommendations mention anemia and serum albumin as the most useful biochemical parameters to stratify frailty status." (PMID 32957481, 2020). "Multivariate analysis showed that sRDW >0.95 was independently associated to patients with anemia (Hb < 10.5) (RR 5.9; CI95%: 2–16.9; p = 0.001), B-symptoms (RR 2.5; CI95%: 1.3–4.9; p = 0.007) and low albumin level (RR 2.2; CI95%: 1.1–4.4; p = 0.019)." (PMID 33158258, 2020). "Other authors have also reported than older age, higher ASA score, anemia, and lower serum albumin increased postoperative complications." (PMID 32493351, 2020). "In the univariate Cox proportional hazards model for OS, variables such as age, stage, total gastrectomy, NLR, LMR, anemia, serum albumin level, PMI, PMABW, PMABSA, PMABMI, and PMMA were significant." (PMID 32913472, 2020). "Multivariate analysis showed that a higher RDW was independently associated with anemia, higher CPR, and low albumin." (PMID 33158258, 2020). "When stratified by severity, we found that patients with severe infections were more likely to have anemia, decreased activated partial thromboplastin time, calcium, and albumin, and increased D-dimer and interleukin-6 (P < 0.05)." (PMID 32582740, 2020). "First, the focus of attention in the previous study was inflammation, oxidative stress, anemia, dyslipidemia, hyperparathyroidism status, and quality of life, and only five studies were included for estimating the albumin level." (PMID 32490516, 2020).